ICAM1 (intercellular adhesion molecule 1)
Diseases named in the same sentence as ICAM1 in open-access papers (continued):
Sharing a sentence is not in itself a finding about the gene and the disease.
malaria (continued). "Also, increases of a combination of multiple host markers of inflammation and endothelial activation, such as ICAM-1, sTie-2 and sFlt-1, have been observed in cerebral and severe malaria compared to uncomplicated malaria as being able to predict mortality." (PMID 26979504, 2016). "The association between ICAM-1 with BH4 (partial correlation coefficient = -0.38, p = 0.035) and the BH4/BH2 ratio (partial correlation coefficient = -0.40, p = 0.03) remained significant after adjustment for malaria severity." (PMID 25764397, 2015). "Similar approaches could be used to lead to the development of novel treatments candidates to reduce malaria morbidity and mortality but require a good understanding of the variety of IE adhesion to ICAM-1." (PMID 25360558, 2014). "Several lines of evidence support the involvement of ICAM-1 in malaria pathogenesis." (PMID 25360558, 2014). "Additionally, ICAM-1 acts as receptor for pathogens like human rhinovirus and Plasmodium falciparum malaria parasites." (PMID 23936131, 2013). "The heterogeneity of the vascular endothelium in various locations in the body, characterized by the difference in expression levels of CD36 or ICAM-1 may play an important role in determining the type and severity of malaria." (PMID 23967200, 2013). "The level of expression of ICAM1 on monocytes has had an uncertain overall role in malaria." (PMID 22909232, 2012). "When we tested patient isolates for their ability to bind to three different forms of ICAM-1 under static conditions, we saw a broad distribution of adhesion types but an excess of ‘ca’ type in severe malaria (CM and SM other combined, although the majority of ‘ca’ types were in the CM category)." (PMID 21390226, 2011). "Consistent with either of these hypotheses, this study observed that patients with cerebral malaria had significantly higher monocyte ICAM-1 levels compared with those with severe malaria anaemia alone." (PMID 20712868, 2010). "Because the endothelium represents the largest organ in the body, direct assessment of endothelial ICAM-1 in specific organ beds affected by malaria may be a more important but more challenging source to study." (PMID 20712868, 2010). "Further examination of cases stratified by severity and by syndrome may indeed clarify the predictive dualities of the physiology of ICAM-1 in malaria." (PMID 20712868, 2010). "Previous histologic studies in cerebral malaria have demonstrated that ICAM-1 expression may directly contribute to cytoadhesion of malaria infected red cells or may serve to recruit leukocytes to sites of endothelial activation." (PMID 20712868, 2010). "Categories of disease in pediatric malaria may exhibit specific combinations of soluble and cellular ICAM-1 expression." (PMID 20712868, 2010). "In this study isolates from both severe and uncomplicated malaria in Thailand could bind to CD36 while only 45% could bind to wild type ICAM-1 and at lower levels than to CD36." (PMID 19650937, 2009). "Plasmodium falciparum isolates show different abilities to form rosettes and binding to CD36 and ICAM-1 which may contribute to different clinical severity of malaria." (PMID 19650937, 2009). "Since in human malaria cytoadhesion of infected erythrocytes to the vascular endothelium is known to be mediated by ICAM-1, the expression of this adhesion molecule was examined in brain blood vessels of P. berghei-infected wild-type and IP-10−/− mice by immunohistochemistry." (PMID 19343215, 2009). "Plasmodium falciparum isolates from different geographical areas showed variable binding ability to CD36 and ICAM-1 and a wide range of ability to form rosettes, which may contribute to different clinical severity of malaria." (PMID 19650937, 2009). "A recent study on trios from African populations has reported the absence of any association of these two ICAM-1 SNPs with severe malaria phenotypes." (PMID 19055786, 2008).
malaria (continued). "PfEMP1-independent but ICAM-1/LFA-1-dependent events occurring during NK cell activation by Pf highlight the fundamental role of cellular cooperation during innate immune response to malaria." (PMID 17311092, 2007). "In addition, ICAM-1 expression may play a role in the cytoadhesion of malaria-infected red blood cells or in the recruitment of leukocytes to endothelial activation sites." (PMID 36510199, 2022). "Our central finding here is that PfEMP1 variants linked to severe malaria display extensive heterogeneity in binding activity for resting and activated 3D brain microvessels, and differences are at least partially attributable to their combinatorial binding properties for EPCR and ICAM-1." (PMID 31138740, 2019). "IE adhesion to ICAM-1 appears associated with severe malaria, implicating DC4-specific antibodies in clinical protection, as they are acquired early in life by children living in areas where malaria is endemic and are associated with clinical protection from malaria." (PMID 29426042, 2018). "By contrast, in the absence of ICAM-1, infected animals experience less anaemia and weight loss, reduced parasite accumulation in both spleen and liver and higher peripheral blood parasitaemia during acute stage malaria." (PMID 28468674, 2017). "ICAM-1 and CD36 are strong candidate receptors for interactions with iRBC containing mature Plasmodium parasites within the microvasculature at the time of sequestration, in both human infections and rodent model infections, and for the associated development of severe malaria pathologies." (PMID 28468674, 2017). "In conclusion, the increased parasite adhesion to ICAM-1 in children with evidence of intestinal damage is an important finding, which highlights the complex aetiology behind increased susceptibility to gram-negative bacteraemia in children with malaria." (PMID 26830671, 2016). "Thus an increase in sICAM-1 levels may be predictive of increased ICAM-1 expression in the brain microvasculature, and hence the development of cerebral complications in malaria." (PMID 24386348, 2013). "This comparativeanalysis demonstrates the predictability of P. falciparum-IEbinding to the two major cytoadhesion receptors CD36 and ICAM-1 and provides newinsight into how natural selection may be shaping the PfEMP1 binding repertoire toexploit distinct host niches of varying anti-malaria immunity." (PMID 21573138, 2011). "Patients selected for ICAM-1 analysis were deliberately selected to represent three categories of severity-of-illness: uncomplicated malaria treated as an outpatient (UM); malaria survivors with severe malaria anaemia or cerebral malaria treated as in-patients (SM-s); and fatal malaria cases (SM-f)." (PMID 20712868, 2010). "Cellular adhesion of P. falciparum-iRBCs consists of a rolling interaction with ICAM1 and a stationary interaction with CD36 and EPCR on vascular endothelial cells which leads to severe malaria." (PMID 40294074, 2025). "Befitting any general immune response mechanism, various cytokines may potentially modulate ICAM1 expression, of which we have found evidence for statistical association of IL1, IL4 (and its receptor, IL4R), IL6, IL13, TLR2, TLR4, and IFNG (and its receptor, IFNGR1) polymorphisms with malaria." (PMID 37287037, 2023). "We therefore measured plasma levels of DBLβ-specific IgG, the ability of such IgG to inhibit PfEMP1-binding to ICAM-1, and its ability to opsonize IEs for ADCP, using plasma from Beninese children with severe (SM) or uncomplicated malaria (UM)." (PMID 35906450, 2022). "BOEC’s derived from cryopreserved small-volume PBMC samples from Ghanaian malaria patients (n = 8) all expressed EPCR, ICAM-1, thrombomodulin and PECAM-1." (PMID 30300360, 2018). "For example, the KEGG term “Malaria” is enriched in the UP genes in RA due to genes such as CR1, GYPA, ICAM1, PECAM1, and TLR4." (PMID 28491277, 2016).
malaria (continued). "Early studies found that hydroxyurea raised concentrations of ICAM-1 in an in vitro model of SCA, raising concern that this could lead to an increased risk of parasite binding in children with SCA and therefore to increased sequestration and complications (including death) from malaria." (PMID 27339303, 2016). "In malaria, a lower BH4/BH2 ratio correlated with decreased microvascular reactivity (r=0.41; p=0.03) and increased ICAM-1 (r=-0.52; p=0.005)." (PMID 25764397, 2015). "E8B is a malaria strain that expresses a mixture of var genes that, in contrast to CS2, promote binding to CD36 and ICAM-1." (PMID 26149666, 2015). "Both ICAM-1 and VCAM-1, soluble adhesion molecules, are detected at high levels in serum from falciparum patients with severe malaria." (PMID 25889165, 2015). "An increase in ICAM-1, VCAM-1, and E-selectin mRNA was found in HUVEC from patients with different degrees of malaria (uncomplicated, severe, or CM) after co-culturing with iRBC-fed mononuclear cells, however such increase did not appear specific for CM." (PMID 24467887, 2014). "The expression of ICAM-1 and VCAM-1 is consistent with previously reported data indicating these adhesion molecules are expressed during complicated malaria." (PMID 24324686, 2013). "The mechanism of neutropenia in malaria has been postulated to involve increased margination and sequestration of neutrophils as a result of the increased expression of cell adhesion molecules (ICAM-1 and VCAM-1) that occurs in malaria." (PMID 25285308, 2013). "This current study assessed the adhesion of P. falciparum infected erythrocytes under flow (ICAM-1) and static (ICAM-1 and CD36) conditions from children with different clinical syndromes of malaria." (PMID 21390226, 2011). "The ICAM 1 and CD36 genes have also been related to ECM in the mouse models but investigations on the role of these genes in human CM and severe malaria led to inconclusive and often contradictory results." (PMID 20585394, 2010). "In line with a role of FcγRIIIb binding antibodies to DBLβ3 domains, antibody-dependent neutrophil phagocytosis of ICAM-1 and EPCR co-binding IE was higher in uncomplicated malaria (15% median, 8–38% interquartile range) compared to cerebral malaria (7%, 30–15%, p < 0.001)." (PMID 39267089, 2024). "Dual ICAM-1-EPCR binding IE were more common in patients with cerebral malaria than in patients with uncomplicated malaria, whereas CD36 binders were more frequently found in patients with uncomplicated malaria." (PMID 36419237, 2023). "The genes involved in host immune response and binding of the malaria parasite, particularly TGFβ1, IL10 and ICAM1 may play a more significant role in malaria parasitemia in P. falciparum than in P. vivax infection." (PMID 34698295, 2021). "Levels of IgG specific for DBLβ domains from group A, B, and C PfEMP1 binding or not binding ICAM-1 were measured in plasma from Ghanaian children with or without malaria." (PMID 31308082, 2019). "Furthermore, parasite isolates from cerebral malaria patients more frequently exhibited binding to both ICAM‐1 and EPCR, whereas binding to CD36 was more frequent in uncomplicated malaria than cerebral malaria patients." (PMID 30804082, 2019). "In this dataset, parasites expressing PfEMP1 predicted to bind EPCR, but not ICAM-1, were more likely to be found in severe malaria cases (CM plus SA) (p = 0.040)." (PMID 28279348, 2017). "However, Ramos and colleagues deleted ICAM-1 in different cells and showed that only ICAM-1 expressed in leukocytes accounts for experimental severe malaria." (PMID 26491221, 2015). "Testing the binding of parasites from HbAS, HbAC, and HbAA children with malaria to individual receptors (e.g., CD36, ICAM-1, gC1qR, EPCR) as well as to MVECs derived from brain or lung may help to further clarify the binding phenotypes of these parasites." (PMID 24647281, 2014).
malaria (continued). "It is likely that ICAM-1 is not the only receptor involved in CM pathogenesis and, for example, a recent study has associated the ability of IE to bind to EPCR with severe malaria, including CM." (PMID 25360558, 2014). "Isolates from severe malaria patients and particularly from CM demonstrated higher binding to ICAM-1, although this is not seen in all studies." (PMID 25360558, 2014). "Surprisingly, soluble recombinant ICAM-1 expressed in one of the most widely used transient expression systems, human embryonic kidney (HEK) cells and derivatives hereof has only been used for malaria binding assays in very few studies." (PMID 23936131, 2013). "The effects of polymorphisms in a number of genes, including β-globin, G6PD, TNF-α, IFN-γ, CD36, ICAM-1, IL10, IL4R, and LTA, upon the clearance of malaria parasites in African individuals was investigated across five large association studies from Burkina Faso, Cameroon, Kenya, Mali, and Sudan." (PMID 21867552, 2011). "In contrast, ItG parasites selected by binding to purified ICAM-1 protein displayed the ‘bc’ binding signature, which was not prevalent among parasites isolated from children with severe malaria." (PMID 21390226, 2011). "Among 114 children with severe malaria, 55 children with uncomplicated malaria, and 43 non-malaria controls, soluble ICAM-1 levels were significantly higher among those with severe disease compared with either uncomplicated malaria or controls." (PMID 20712868, 2010). "Several human cell receptors, including the extensively studied CD36 and intercellular adhesion molecule 1 (ICAM-1), have been implicated in adhesion, although no consensus on association between receptor binding and severe malaria has been reached." (PMID 20862303, 2010). "Soluble ICAM-1 levels were significantly higher (p < 0.001) among those with malaria (735 ng/mL) compared with controls (440 ng/mL), but did not discriminate those with cerebral malaria." (PMID 20712868, 2010). "Patients with UM had higher monocyte ICAM-1 expression consistent with a role for monocyte ICAM-1 in immune clearance during non-severe malaria." (PMID 20712868, 2010). "Among those with both severe and non-severe malaria, they observed higher monocyte ICAM-1 expression at onset of disease compared with convalescence." (PMID 20712868, 2010). "The aim of this study was to investigate the association of SNPs of three adhesion molecule genes, ICAM1, PECAM1 and CD36, with severity of falciparum malaria in a malaria-endemic and a non-endemic region of India." (PMID 19055786, 2008). "Interestingly, in another small cohort, total IgG targeting full length DC13 (which is dual ICAM-1 and EPCR binding) was boosted in individuals with uncomplicated malaria from presentation to convalescence, whereas IgG1 and IgG3 to this protein were boosted in convalescence from cerebral malaria." (PMID 36419237, 2023). "ICAM‐1 was blocked with antibodies in both HBMEC and HDMEC, while CD36 was blocked in HDMEC, and in all conditions, antibodies could block ~ 50% of adhesion independently of the parasites originating from cerebral malaria or uncomplicated malaria cases." (PMID 30804082, 2019). "Placentas from malaria-infected litters (wild-type and C5ar-/-) showed placental inflammation as indicated by increased expression of tumor necrosis factor (TNF), interferon gamma (IFNΥ), intracellular adhesion molecule-1 (ICAM-1) and monocyte chemotactic protein 1 (MCP-1, CCL2) (p < 0.05)." (PMID 26402732, 2015). "In addition to being useful in malaria research, the HEK239 cell-produced protein might also be useful in other research areas, as ICAM‐1 also acts as a receptor for cells of the immune system and viruses such as human rhinovirus." (PMID 23936131, 2013). "However, among those with severe malaria syndromes, soluble ICAM-1 levels did not distinguish cerebral malaria or severe malaria anaemia from other malaria syndromes." (PMID 20712868, 2010).
malaria (continued). "Importantly, and of physiological relevance to adhesion and malaria pathogenesis, this parasite sub-line was found to bind both CD31/PECAM1 and CD54/ICAM1 and to adhere twice as efficiently to human endothelial cells, compared to infected cells having only one PfEMP1 variant on the surface." (PMID 20824088, 2010). "Also consistent with previous work, soluble ICAM-1 levels did not distinguish patients with cerebral malaria from those with severe malaria anaemia." (PMID 20712868, 2010). "Another line of evidence is the association between CM and a homozygous mutation in ICAM-1 in Kilifi, Kenya, named ICAM-1Kilifi, although it should be noted that other studies such as those in the Gambia and Thailand have not shown an association between ICAM-1Kilifi and severe malaria." (PMID 25360558, 2014).